VIM (vimentin)
Diseases named in the same sentence as VIM in open-access papers (continued):
Sharing a sentence is not in itself a finding about the gene and the disease.
tumor (continued). "In TN disease, macrophage/tumor and B/T lymphocyte neighbors were enriched, and lymphocytes were dispersed in good-prognosis tumors, while tumor cell neighborhoods containing vimentin+ fibroblasts were enriched in poor-prognosis tumors." (PMID 39808504, 2025). "Further, vimentin-expressing tumor cells were described to be poorly differentiated and showed properties linked to infiltration and malignancy." (PMID 40558484, 2025). "The tumour cells showed immunohistochemical expression of vimentin and SMA, with focal expression of calponin and CD10." (PMID 41357577, 2025). "Researchers focussed on Frizzled 9, GFAP, CD133, Vimentin, and SSEA4, which are associated with stem cell self-renewal, differentiation, and tumour initiation." (PMID 39316249, 2025). "The presence of S100A4 and vimentin in WT-EVs suggests their combined role in shaping tumor plasticity and immune evasion." (PMID 40618999, 2025). "Results showed increased expression of N‐cadherin, vimentin, Slug, and Snail in tumor cells treated with Fn." (PMID 40433907, 2025). "Immunohistochemically, the tumor cells in PHA demonstrate positivity for vimentin and the vascular lineage markers, including ERG, CD31, CD34, FLI-1, and factor VIII-related antigen." (PMID 41367857, 2025). "Studies have shown that vimentin contributes to tumor progression by mediating cytoskeleton architecture and maintaining intracellular mechanical homeostasis." (PMID 40666093, 2025). "The expression of Vimentin, Snail, and Slug was significantly reduced in the tumor tissues obtained through xenografts using miR-22-3p stable cells and galectin-1 knockdown cells." (PMID 39996781, 2025). "The biopsy specimens were stained for Ki 67, e-cadherin, vimentin, programmed-death ligand 1, and tumor-infiltrating lymphocytes (TIL, all CD45 positive cells)." (PMID 40691330, 2025). "The tumor cells were positive for vimentin and MDM2, confirming the diagnosis of aortic intimal sarcoma." (PMID 40012551, 2025). "A comprehensive analysis was conducted to evaluate potential biases and diagnostic efficacy in demographic and clinicopathological characteristics, including age, gender, and tumor stage, of the Vimentin/POU4F2 combined methylation panel in urine DNA." (PMID 41029537, 2025). "PARP3 knockdown significantly suppresses the metastasis-promoting proteins Vimentin and N-cadherin, while concomitantly upregulating the expression of the epithelial tumor suppressor E-cadherin." (PMID 41008918, 2025). "A positive correlation between Ki-67 expression and serum creatinine (SCR) levels (r = 0.337, P = 0.017), between Vimentin expression and tumor size (r = 0.400, P = 0.04) is suggested." (PMID 40831933, 2025). "We observed that bacterially colonized cancers had higher PMN counts and increased expression of vimentin in tumor cell areas." (PMID 40155451, 2025). "The results showed that E‐cadherin expression was downregulated in tumor tissues of A549 cells transfected with the miR‐224‐5p inhibitor, while N‐cadherin and vimentin expressions were upregulated." (PMID 39840666, 2025). "These tumors are highly infiltrative and exhibit significant therapy resistance, characteristics that align with the increased vimentin positivity observed in their tumor cells." (PMID 40937216, 2025). "IHC staining of vimentin in tumor tissues from HSC-3M/shSTAT3+shHRH1-injected mice showed the lowest expression compared to tumor tissues from either HSC-3M/shHRH1- or HSC-3M/shSTAT3-injected mice." (PMID 40113769, 2025). "Tumor cells showed strong nuclear β-catenin expression and were positive for Vimentin, with a Ki-67 proliferation index of approximately 10%." (PMID 41367864, 2025). "On Immunohistochemistry (IHC), tumor cells show positivity for vimentin, with variable reactivity for actin, desmin, and CD34." (PMID 40092021, 2025).
tumor (continued). "Immunohistochemically, the tumor was positive for vimentin, EMA, PgR, TTF-1, and somatostatin receptors-2, and negative for cytokeratin, Bcl-2, CD34, and S-100, with a Ki-67 index of approximately 5%." (PMID 40265140, 2025). "Concurrently, pathway activation stimulates the expression of vascular endothelial growth factor (VEGF) and enhances stromal markers, including N-cadherin and vimentin, thereby facilitating tumor growth and metastasis." (PMID 41409300, 2025). "IHC staining demonstrated that, compared to the NC group, the sh-WTAP group showed downregulation of WTAP, along with a marked reduction in the expression of tumor markers Ki-67 and vimentin." (PMID 40707002, 2025). "Expression of ECAD and VIM were quantified in cells identified as the tumor using Akoya InForm software." (PMID 41278700, 2025). "Several key markers define E-cadherin is often downregulated in aggressive CRC, whereas mesenchymal markers such as N-cadherin, vimentin, and matrix metalloproteinases are upregulated, facilitating tumor invasion and metastasis." (PMID 40134588, 2025). "By showing that EV-associated vimentin induces EMT in epithelial cells, we highlight its role in cell-cell communication, particularly in the tumor microenvironment and wound healing." (PMID 40618999, 2025). "The NSCLC mouse model we constructed showed that shAJUBA inhibited the xenograft growth in models using NSCLC cells, and AJUBA ablation suppressed the expression of Ki67, p-ERK, β-catenin, N-cadherin and Vimentin simultaneously in tumor tissues." (PMID 40240814, 2025). "We further present a visualization of gene expression dynamics for MYB, CD24, CDH11, and VIM along with the spatial pseudotime trajectory, highlighting the progressive transcriptional shifts asso1ciated with tumor progression and EMT56." (PMID 40950184, 2025). "Early FDIM showed upregulation of genes linked to tumour initiation, immune recruitment, and motility (e.g., STOX1, PEG3, XIAP, MCAM, VIM)." (PMID 40683913, 2025). "Immunohistochemical results showed that the tumor cells expressed Vimentin, SMA, Bcl-2, CD56, CD34, CD31, Ki-67, ERG, RB, INI-1, and SATB2, but were negative for SSTR2 and CK." (PMID 40406261, 2025). "Colocalization studies showed that CD70 protein exhibits a fluke, diffuse signal with a conspicuous complementarity with vimentin staining in tumor nests of CD70-high patients." (PMID 40205178, 2025). "EMT-related proteins [mediator of ErbB2-driven cell motility 1 (MEMO1), E-cadherin, fibronectin, vimentin, and vinculin] were quantified by Western blotting in tumor and adjacent normal mucosa." (PMID 40507970, 2025). "This overlapping expression of CXCL5 within the vimentin positive stroma was consistently observed in the patient tumor tissues." (PMID 41392310, 2025). "Tumor cells also showed diffuse positivity for vimentin and PAX8 and focal positivity for CK7 and CD10." (PMID 40361930, 2025). "Fisetin has also been shown to inhibit EMT by upregulating the epithelial marker E-cadherin and downregulating mesenchymal markers, including vimentin and N-cadherin, in various tumor cells." (PMID 41305575, 2025). "Circulating tumor cells (CTCs) are tumor cells derived from primary tumors that can be categorized as epithelial (EpCAM+Vimentin−), mesenchymal (EpCAM−Vimentin+), and hybrid (EpCAM+Vimentin+) types." (PMID 40995085, 2025). "The tumor cells showed positive expression for Vimentin, ERG, MUC4, TLE1, CD99, CD56, Ki67 (approximately 80%), and H3K27Me3." (PMID 40144208, 2025). "In contrast, the splenic injection model using KPCPb–/– mouse PDAC cells with shRNA knockdown of the vimentin gene showed a reduced metastatic tumor burden compared with KPCPb–/– mouse PDAC cells with control shRNA." (PMID 40454484, 2025).
tumor (continued). "In vitro, the pharmacological inhibition of CD26 reduced Vimentin expression and had an anti-proliferative effect in tumor cell lines." (PMID 41426321, 2025). "Increased E‐cadherin tumour levels.Increased levels of apoptosis.Decreased vimentin, N‐cadherin, tumour volume, and tumour weight.Decreased tumour levels of oncoprotein E6 and E7." (PMID 40888184, 2025). "A significant decrease in vinculin expression was observed in tumor tissue compared with healthy mucosa (mean ± SD: 0.75 ± 0.51 vs. 1.46 ± 0.89, p < 0.001), as well as in vimentin (0.78 ± 0.80 vs. 4.08 ± 4.88, p < 0.001)." (PMID 40507970, 2025). "The expression of VIM predicts less tumor metastasis and higher overall survival in EC, making it an excellent prognostic biomarker for this cancer." (PMID 40511304, 2025). "EMT, characterized by the loss of epithelial markers such as E‐cadherin and the acquisition of mesenchymal markers like Vimentin and N‐cadherin, plays a critical role in promoting tumor cell invasion and metastasis." (PMID 40035259, 2025). "On the other hand, it facilitates epithelial-mesenchymal transition (EMT) by regulating the expression of vimentin and N-cadherin, thereby promoting migratory and invasive capacities of tumor cells." (PMID 41358198, 2025). "We demonstrated that one of the glial cell astrocytic markers, vimentin, was positive in tumor tissue, particularly in areas displaying astrocytic appearances." (PMID 38473403, 2024). "While these tumor cells express S-100 and vimentin, their reactivity to glial fibrillary acidic protein is variable." (PMID 39070413, 2024). "Immunohistochemistry showed that tumor cells positively expressed vimentin, SMA, and Desmin usually, and CK, CD68, CD30 and ALK were partially expressed positively, while CD117 and CD34 were usually negative expressed." (PMID 39193013, 2024). "Histologisch zeigte sich, dass der Tumor aus dicht gelagerten großen histiozytenartigen Zellen mit Expression von Vimentin, CD68 und CD163 sowie Negativität für Keratin, Langerin und SMA aufgebaut ist." (PMID 38472383, 2024). "Different protein immunohistochemistry double immunostaining scores show that the expression levels of NDRG1 and Vimentin are correlated with tumor grade in HGG patients." (PMID 39668822, 2024). "In our case, the presence of vimentin-positive staining confirms the mesenchymal nature of the tumor." (PMID 39896188, 2024). "We also observed less apoptosis and changes in EMT marker expression with decreased cytokeratin and increased vimentin expressions in the tumor tissue, which confirms the huge impact of miR-147b on tumor progression." (PMID 38396293, 2024). "Experimental and clinical studies have further demonstrated the gatekeeper role of epithelial-to-mesenchymal transition (EMT) in modulating tumor invasion and metastasis, where CDH2 and VIM have been underlined to be involved." (PMID 39735560, 2024). "The embryonal HBTOs were enriched with WNT target genes and EMT markers, including AXIN2, LEF1, DKK1, NOTUM, NKD1 and VIM, in line with the embryonal tumor signature." (PMID 39567475, 2024). "In the mesenchymal stage, the tumour cells show higher vimentin expression, but the expression of E-cadherin is repressed." (PMID 38540190, 2024). "Vimentin is not only involved in EMT but also associated with CSCs, promoting resistance to apoptosis and tumor invasion, key elements in metastatic progression." (PMID 39766136, 2024). "The distribution of fibroblasts at the invasive front and tumor-adjacent adipose tissue was analyzed by vimentin staining." (PMID 39456610, 2024). "Pan-CK was positive in the epithelial component of the tumor, while vimentin was positive in high-grade sarcomatous components." (PMID 39588415, 2024). "Vimentin-positive staining and ER positivity strongly suggested the high likelihood of a secondary tumor originating from the previously known EC." (PMID 39318944, 2024).
tumor (continued). "The tumor cells were immunohistochemically positive for vimentin, also they were positive for striated muscle markers, such as desmin & myogenin but negative for SMA." (PMID 39020398, 2024). "Further studies revealed that glabridin decreased the expression of neural cadherin (N-cadherin) and vimentin, and upregulated the expression of epithelial cadherin (E-cadherin) in tumor cells." (PMID 39723390, 2024). "The new knowledge generated is the computed score for CD44, EGFR, E-cadherin, and vimentin, which can be used as indicators to predict tumor aggressiveness by implicating recurrence." (PMID 39050298, 2024). "Immunohistochemically, the tumor was positive for vimentin, SF1, CD56, and beta-catenin, which aligns with findings reported in the literature." (PMID 40071053, 2024). "Immunohistochemical stains demonstrate the tumor cells to be strongly positive for vimentin, pankeratin, CK7, CK20, chromogranin, synaptophysin, CD45, and focally positive for CD56." (PMID 38933829, 2024). "We performed further an immunohistochemical examination, revealing that the tumor area was positive for vimentin and SATB2, while CK5/6 and SMA were negative." (PMID 39568569, 2024). "This pattern was present in the original tumor tissues, as Esc tumors showed decreased expression of the epithelial marker E-cadherin and increased expression of the mesenchymal markers Vimentin and Twist." (PMID 38378697, 2024). "In contrast, others, such as EpCAM and vimentin, are present in every tumor cell and can be potentially used to detect every type of CTCs." (PMID 37874534, 2024). "The Western blot experiment showed that the EMT pathway of tumor cells was significantly upregulated when adding the matrix gel, manifested as the upregulation of Vimentin and Snail and downregulation of beta-Catenin and E-cadherin." (PMID 38987529, 2024). "Histologically, the tumor was found to consist of densely clustered large histiocyte-like cells with expression of vimentin, CD68, and CD163 as well as negativity for keratin, langerin, and SMA." (PMID 38472383, 2024). "An immunohistochemical analysis was performed, revealing that the tumor cells were strongly positive only for vimentin." (PMID 39449379, 2024). "Immunohistochemistry of tumor specimens shows enhanced GSDMC protein expression for invading vimentin+ PDAC cells in vivo and ex vivo spheroids." (PMID 39297408, 2024). "At termination, i.e., 18 weeks EMT proteins including E-cadherin, N-cadherin, Vimentin and Fibronectin were checked in tumour sections." (PMID 38519574, 2024). "Among stromal fibroblast cells, ITGAV, ITGA1, ITGB1, and ITGB5 were significantly upregulated following IO and, notably, isolated tumor cells found in the stroma showed upregulation of B2M, VIM, ITGA5, ITGB2, and ITGA3." (PMID 39639369, 2024). "Immunohistochemistry remains the cornerstone for a definite diagnosis when S100 protein and vimentin show positivity for tumor cells and the proliferation index (Ki67%) is low." (PMID 39219899, 2024). "As a result, tumor cells treated with nicotine demonstrate increased expression of mesenchymal markers such as vimentin, SNAIL, and PrX1 proteins while showing decreased levels of epithelial markers such as E-cadherin." (PMID 38539520, 2024). "In vivo experiments also demonstrated that N-cadherin and Vimentin were highly expressed in tumor cells of circDCAF8 overexpression group, and upregulation of circDCAF8 promoted HCC lung metastasis." (PMID 38816735, 2024). "In terms of function, circGLIS3 plays a role in promoting GC progression by sponging the tumor suppressor miR-1343-3p and regulating the phosphorylation of VIMENTIN Ser83." (PMID 38459513, 2024). "miR-200c delivery also resulted in significant down-regulation of β-catenin, ZEB1, vimentin, and N-cadherin expression in the tumor." (PMID 39198318, 2024).
tumor (continued). "Immunohistochemically, the tumour cells showed intense positivity in the vimentin (VIM) reaction, as well as clear positivity in the neuron-specific enolase (NSE) reaction, variable expression of S-100 protein, and subtle CD56 positivity." (PMID 39582714, 2024). "The tissue sections were selected to contain the invasive tumor front, and the E-cadherin and Vimentin score were determined." (PMID 39061649, 2024). "Immunohistochemistry can reveal specific markers for this type of tumor, such as S100 protein (+), vimentin (+), and glial fibrillary acidic protein (GFAP) (−), among others." (PMID 39444783, 2024). "Immunohistochemical staining for Vimentin revealed that over 95% of isolated cells within the tumor are positive for Vimentin, indicating a significant presence of mesenchymal characteristics." (PMID 39062740, 2024). "Not only that, but we also found that Vimentin protein is also elevated with ERβ, and Vimentin upregulation reflects the high differentiation plasticity of tumor cells." (PMID 38641065, 2024). "EMT related proteins including N-cadherin, E-cadherin, and Vimentin have been believed to play a vital in the tumor metastasis." (PMID 38230211, 2024). "Paterlini-Bréchot and her research group detected CTCs in all of the six SS patients being studied using the ISET (isolation by size of tumor cells) system and defining CTCs as either vimentin+CD45−CD34− or panCK+CD45-CD34−21." (PMID 38811642, 2024). "Pan-Cytokeratin has been reported to stain the carcinomas (epithelial tumor cells) and it highlights tumor cell budding (detachment) at the invasive front.Vimentin is expressed in mesenchymal cells and correlated with the malignancy of cancer cells." (PMID 38612832, 2024). "Previous studies have shown that vimentin and N-cadherin mRNA and protein are significantly greater in the tumor tissues of NSCLC patients than in neighboring tissues, whereas E-cadherin expression is significantly lower." (PMID 38424624, 2024). "Vimentin is expressed in some tumor cells, some activated microglia, as well as all endothelial cells and some pericytes." (PMID 38295184, 2024). "The descriptive statistical analysis of IHC-based protein expression of vimentin in both tumor glandular and tumor stromal parts of tissues revealed stronger intensity patterns in EBV-positive tissues (n = 39) compared to EBV-negative (n = 60) PCa tissues." (PMID 38705879, 2024). "We then detected the expression of E-cadherin and vimentin expression for epithelial-mesenchymal transition using IHC in the mouse tumor samples." (PMID 37978163, 2024). "Determined in tumor tissues, expression profiles of E-cadherin and vimentin agreed with the in vitro experimental findings, indicating that ePPMO-146b possibly inhibited epithelial-mesenchymal transition in vivo." (PMID 37978163, 2024). "Commonly used markers for NF include SMA, muscle-specific actin, vimentin, and calponin, all of which highlight the myofibroblastic nature of the tumor." (PMID 39445266, 2024). "As E-cadherin decreases, the mesenchymal cell markers N-cadherin and vimentin increase and support tumor cell survival and migration." (PMID 39555068, 2024). "N-cadherin and vimentin are markers of mesenchymal cells, and their expression suggests that tumor cells have acquired the ability to transform into mesenchymal cells." (PMID 38879666, 2024). "Immunohistochemistry showed positive staining for cell CyclinD1, CD10, Caldesmon, and Vimentin in the tumor cells, with some tumor cells also demonstrating positive labeling for MyoD1, CKpan, and Myogenin." (PMID 39009979, 2024). "Our study demonstrated that Tan IIA inhibited tumor growth and suppressed cell migration by increasing E-cadherin expression and decreasing vimentin expression." (PMID 38297301, 2024).